CTLA4 (cytotoxic T-lymphocyte associated protein 4)
Diseases named in the same sentence as CTLA4 in open-access papers (continued):
Sharing a sentence is not in itself a finding about the gene and the disease.
tumor (continued). "We provide evidence that high FOXP4-AS1 expression plays a tumor suppressive role in OVs by participating in biological processes and pathways including PD-1 signaling, the CTLA4 pathway, the B cell receptor signaling pathway, apoptosis, signaling by FGFR, and the JAK-STAT signaling pathway." (PMID 34622876, 2021). "Anti-CTLA4 therapy has been shown to increase T cell diversity in the peripheral blood of cancer patients, though this was not necessarily reflected in positive phenotypic changes in the tumor." (PMID 33968757, 2021). "This feature could partially explain the failure of these therapies in preventing tumor relapses in patients treated with anti-CTLA-4 and/or anti-PD-1/L1 mAbs or CAR T cells." (PMID 34345218, 2021). "Regarding the effect of Tregs, several preclinical studies indicated that the anti-tumor effects of CTLA-4 blockade were dependent on the depletion of CTLA-4-expressing Tregs in the tumor microenvironment via antibody-dependent T cellular cytotoxicity, leading to an increase in the CD8+/Treg ratio." (PMID 34526990, 2021). "However, Tregs in the tumor microenvironment also express both PD-1 and CTLA-4 at a high level compared to effector T cells." (PMID 33717139, 2021). "Examples include RIVAL 01/TBio-6517, a Vaccinia virus for tumor-directed expression of FLT3L, anti-CTLA-4, and IL-12 (NCT04301011), and ONCR-177 (NCT04348916), an HSV-1 mediating expression of IL-12, FLT3LG, CCL4, anti-PD-1, and anti-CTLA-4 to enhance induction of tumor-specific adaptive immunity." (PMID 33863363, 2021). "This discrepancy whether CTLA-4 expression in tumor cells has a good prognostic impact or a bad impact is due to much less data known about its expression and function in tumor cells." (PMID 33906311, 2021). "The differential contributions of the CTLA-4 and PD-1 co-inhibitory receptors create diverse expression phenotypes, which may explain the varied efficacy of ICIs across tumor types, as well as their distinct toxicity profiles." (PMID 34675810, 2021). "CTLA-4 is known to be expressed on several tumor-derived human cell lines." (PMID 34376232, 2021). "CTLA-4 is crucial at the priming stage of naïve anti-tumor T cell responses by professional antigen presenting cells (APC), and therefore its blockade has the potential to generate de novo powerful CD8+ cytotoxic and CD4+ helper T cell anti-tumor effector responses." (PMID 35069536, 2021). "The level of expression of immunoregulators in tumor tissue could be also relevant to anticipate response to immune checkpoints inhibitors targeting PD-1/PD-L1 or CTLA4." (PMID 33106940, 2021). "Co-stimulation of the immune system with tumor antigens via cryosurgery in the presence of a “primed” immune system, pretreated with CTLA-4 and PD-1 combination therapy, would theoretically result in a synergistic effect of local tumor and distant metastasis regression or an abscopal effect." (PMID 33671258, 2021). "The risk factors associated with CIC recurrence included early irAE development, long duration of the initial CIC, initial application of immunosuppressants, pneumonitis, hepatitis, age over 65, advanced tumor stage, CTLA-4 inhibitors use, and less antibiotic therapy." (PMID 34992611, 2021). "Since we observed increased Tregs in TME of CD200R-deficient tumors, we also examined if anti-CD200 could inhibit tumor growth in combination with anti-CTLA4 antibody 9H10." (PMID 34692697, 2021). "In a proof-of-concept study, [177Lu]Lu-DOTA-folate was applied to NF9006 tumor-bearing mice to investigate whether this radiation stimulus would have an impact on the efficacy of anti-CTLA-4 immunotherapy." (PMID 33078260, 2021). "Because ICIs activate tumor immunity by inhibiting PD-1/PD-L1/CTLA-4, they might also simultaneously inhibit immunity to infection." (PMID 34122422, 2021). "Interestingly, the authors also observed improved control of the irradiated tumor when using a single RT dose of 8 Gy with anti-CTLA-4 mAb." (PMID 33530329, 2021).
tumor (continued). "Finally, MRT combined with anti-CTLA-4 ablated the tumor in half of the cases, and induced prolonged systemic antitumor immunity." (PMID 35008319, 2021). "Similarly, checkpoint blockade therapy (anti-PD-1, anti-PD-L1, anti-CTLA-4) corrects nutrient restriction experienced by T cells in a progressing tumor by upregulating CD28 mediated glycolysis." (PMID 33807867, 2021). "These interesting findings could encourage the evaluation of an association of proton therapy with for example an anti-CTLA4 or an anti-CCR4, which, by targeting Tregs, induce reactivation of CD8+ T cells against tumor cells." (PMID 34188135, 2021). "Survival analysis showed that a lower classifier index reflected better prognosis for STAD patients, and the index showed correlation with expression of immune checkpoint molecules (PD1, PDL1, and CTLA4), tumor-infiltrating lymphocytes, and microsatellite instability." (PMID 33644056, 2021). "The combination with the vaccine is predicted to improve the efficacy of the mono-therapy, since the corresponding optimal protocol provides a faster tumor reduction, while administering a lower amount of anti-CTLA4, with a consequent reduction in ipilimumab-related toxicity." (PMID 35008298, 2021). "Anti-CTLA-4 antibodies selectively mediated the reduction of regulatory T cells (Tregs) at tumor sites, inhibited the negative regulatory effects on tumors, and enhanced anti-tumor effects." (PMID 34743730, 2021). "In addition, inhibitors targeting CTLA-4 can block the binding of CTLA-4 to B7, inhibit the production of T cell suppression signals and enhance specific anti-tumor immune response." (PMID 33819967, 2021). "Loss of Th1 responses leading to tumor progression could point towards increase in apoptosis of CD4+ T cells via Fas pathway or tolerance to tumor antigens (for instance, CTLA-4 and PD-1)." (PMID 34899753, 2021). "Moreover, studies in numerous animal models have shown that combination therapy with curcumin and the immune checkpoint inhibitor, anti-CTLA-4, significantly suppressed tumor growth." (PMID 34248973, 2021). "Most importantly, tumours might escape immunosurveillance by activating checkpoint blockades by the expression of PD1, PD-L1, CTLA4 and others by tumour cells and immune cells to prevent the activation of cytotoxic T cells for tumour cell killing." (PMID 33824479, 2021). "Our analysis of Treg subpopulations suggests that the decreased immunosuppressive potential of Treg cells in TC-1/dCD80-1-induced tumors after CTLA-4 blockade might also contribute to the anti-tumor effect of anti-CTLA-4 therapy in these tumors." (PMID 33923750, 2021). "For instance, sorafenib and IFN-α combined with herbal compound inhibited the EMT of HCC cells after iRFA; bevacizumab inhibited the tumor growth and angiogenesis induced by iRFA; and CTLA-4 blockade suppressed the growth of residual tumors and improved survival in a subcutaneous murine HCC model." (PMID 34975896, 2021). "We sought to test whether local tumor destruction by IRE followed by anti-CTLA-4 therapy would also perform an in situ vaccination function." (PMID 34162858, 2021). "Importantly, CTLA4 blockade has been studied extensively as checkpoint inhibitor in cancer immunotherapy, since CTLA4 is often upregulated by tumor cells for immune evasion." (PMID 33679808, 2021). "This may be because the expression of CTLA-4 by Tregs in the tumor may be significantly higher than in the peripheral lymphatic organs." (PMID 34692696, 2021). "A lower DMS, characterized by increased CTLA-4/PD-1/L1 gene expression, greater methylation modifications, and tumor mutation burden, characterized a noninflamed phenotype with worse survival." (PMID 34552879, 2021). "Lastly, we observed CTLA-4 expression on activated TREGs for various disease and tumour models." (PMID 34793567, 2021).
tumor (continued). "Interestingly, clear trends indicated that risk score positively correlated with tumor microenvironment (TME) scores and immune checkpoints TIGIT, CTLA4, and BTLA." (PMID 34712369, 2021). "Given the breakthrough advancements achieved by inhibition of CTLA-4 in several advanced tumor entities and the evidence on its functional relation to TIRC7, TIRC7 should be considered a potential new upstream molecule to be addressed therapeutically in CCA and other solid tumors." (PMID 34944891, 2021). "Higher tumor mutation burden (TMB-H) has been viewed as a predictive biomarker for better responses of cancer patients to anti-PD-1 and anti-CTLA4 therapy, because the increasing numbers of mutant-protein-derived tumor antigens allow the enhanced immunogenicity." (PMID 34834551, 2021). "In this work, we employ a mathematical model of CRPC to determine the optimal administration protocol of ipilimumab, a particular anti-CTLA4, as single treatment or in combination with the sipuleucel-T, by considering both the effect on tumor population and the drug toxicity." (PMID 35008298, 2021). "This leads us to hypothesize that the presence of activated NK cells already within tumors improves tumor clearance mediated by anti-CTLA-4." (PMID 34376232, 2021). "There are several pieces of evidence showing that ICI, specifically, anti-PD-1 and anti-CTLA-4 that are currently used in clinical practice may induce a destabilized phenotype in tumor Treg cells." (PMID 34539668, 2021). "Ipilimumab is an IgG1 monoclonal antibody against the extracellular domain of CTLA-4 that prevents T cell suppression by inhibitory immune checkpoints, resulting in a potent anti-tumour effect by enhancing effector cells and inhibiting regulatory activity of T cells." (PMID 33917882, 2021). "Multiple investigations have uncovered the inhibitory checkpoint inhibitors expressed on NK cells in tumor microenvironment, including the famous PD-1, CTLA-4 as well as newly identified NKG2A, TIGIT, which are now appreciated as promising targets for NK cells-based immunotherapy." (PMID 33262461, 2021). "Furthermore, ccRCC is also distinguished as a highly inflamed tumor, with high levels of tumor infiltrating lymphocytes, and a predominant expression of immune checkpoints, such as PD-L1 and CTLA-4." (PMID 34885091, 2021). "Therefore, anti-tumor activity of nivolumab and ipilimumab, an anti-CTLA-4 antibody as combinatorial therapy is currently under evaluation in phase II clinical trial in patients with rare tumor types, including NPC (NCT02834013)." (PMID 34066342, 2021). "Although B. fragilis frequency keeps stable after anti-CTLA-4 therapy, the elevated number of B. fragilis could further decrease the size of tumor in patients treated with ipilimumab." (PMID 34992611, 2021). "Altogether, the results obtained suggest that diseased cats presenting the most aggressive tumor subtypes could take advantage of resorting to immune-targeted therapies (e.g., anti-PD-1, anti-CTLA-4, or anti-VISTA)." (PMID 34771722, 2021). "The combination of immune checkpoint blockade with immunotherapies such as CTLA-4, PD-1, and PD-L1 inhibitors is a promising approach to treat a variety of malignancies, and an activated tumor immune microenvironment is correlated with good outcomes of immune checkpoint inhibitor treatment." (PMID 34312372, 2021). "The current hypothesis proposes that anti-CTLA-4 ipilimumab leads to a more favorable tumor environment for improved efficacy with concurrent or sequential anti-PD-1 therapy." (PMID 35087529, 2021). "The role of CTLA-4 in tumor cells, however, is barely understood." (PMID 33196890, 2021). "Recently, a bi-specific molecule which targets simultaneously CTLA-4 and TGF-β (a-CTLA4-TGFβRII) has been tested in preclinical models of adult solid tumors, showing an increased anti-tumor activity as compared to drugs targeting CTLA-4 alone, due to Treg inhibition." (PMID 33920505, 2021).
tumor (continued). "Moreover, the immunotherapeutic efficacy of several immune checkpoint inhibitors (ICIs) (anti-CTLA4/PD-L1/PD-1, 8) has widely assessed and has achieved a notable response in tumor treatment, including LUAD." (PMID 34552879, 2021). "PD-L1 and CTLA-4 expression by tumour cells could cooperate with each other in enhancing progression of CRC leading to poor patient outcome, while their expression by TILs could stand against tumour progression." (PMID 35047074, 2021). "The downregulation of PD-1 was also observed in Tregs isolated from tumor tissues following AICAR treatment, and combination therapy with AICAR with anti-CTLA4 antibody significantly reduced the tumor growth due to increased antitumor T cell activity in comparison with AICAR monotherapy." (PMID 34649584, 2021). "One study investigated the effect of combining CD3xEGFR-armed T cells with Treg-depleting ipilimumab (anti-CTLA-4) on T-cell activation and proliferation when co-cultured with tumor cell lines or primary tumor cells and found enhanced T-cell-mediated cytotoxicity and increased T-cell proliferation." (PMID 33466732, 2021). "Given their expression of PVR, TNFRSF14 and CD80/CD86, they might be under direct control by TIGIT+CTLA4+CSF2+TNFSF14+ tumor cells." (PMID 33968070, 2021). "Indeed, the high expression of PD-1, CTLA-4, LAG-3, and TIM-3 in the tumor microenvironment has been associated with the attenuated T cell-mediated antitumoral immune responses." (PMID 34947886, 2021). "Similarly, CTLA-4 also behaves as an immune checkpoint downregulating tumor-reactive T-cell activation, clonal expansion and subsequent tumor rejection." (PMID 33800796, 2021). "Moreover, this strategy further increased the anti-tumor efficacy of PD-1 or CTLA-4 blockade in previously resistant tumors." (PMID 33777008, 2021). "Moreover, T-regulatory cells constitutively express CTLA4 which further plays a critical role in the dampening of anti-tumor immunity." (PMID 33466402, 2021). "Moreover, this study also demonstrated that fecal microbiota transplantation (FMT) of human Bacteroides spp.-rich feces significantly increases the overall outcome of tumor bearing animals by markedly increasing the response to CTLA-4 blockade." (PMID 34638420, 2021). "Recently, tandem peptide nanocomplexes (TPNCs) carrying CpG DNA (TLR9 agonists), which stimulate TAM inflammatory gene expression, were shown to suppress tumor growth and synergize with CTLA-4 inhibition in primary BC models, warranting investigation of this strategy for BCBMs." (PMID 34716900, 2021). "These analyses yield novel insights into the role of NK cells in anti-CTLA-4 efficacy and represent a general strategy for the study of shared tumor biology across datasets derived from different tumor types, treatment groups, sequencing platforms, and species." (PMID 34376232, 2021). "However, adoptive transfer of CD8+ TILs with dual antibody blockade of PD-1 and CTLA-4 in vitro still demonstrates killing tumor ability in vivo." (PMID 33406733, 2021). "These intriguing findings support the hypothesis of reciprocal modulation among these specific immune checkpoints and highlight for the first time the existence of a crosstalk also in tumor cells involving not only PD-L1 and its receptor PD-1, but also CTLA-4." (PMID 34201082, 2021). "Subsequently, the blockade of CTLA-4 could re-activate the T cells, and CTLA-4 blockade antibody could induce tumor rejection in mice." (PMID 34885172, 2021). "Notably, while CTLA-4 blockade has shown efficacy in numerous mouse tumor models, this appears largely dependent on the stage of disease and tumor burden." (PMID 34025662, 2021). "However, more recent studies discover that anti-CTLA-4 mAbs predominantly deplete Tregs in the TME to promote the anti-tumor immune response." (PMID 34806028, 2021).
tumor (continued). "Here, we investigated the effects of anti-PD-1, anti-PD-L1 and anti-CTLA-4 immunomodulatory mAbs on different tumor cells by choosing in particular breast and lung cell lines, as many ongoing clinical trials are evaluating the efficacy of immunomodulatory mAbs on these tumors." (PMID 34201082, 2021). "Future transfer learning analyses on large cohort studies of anti-CTLA-4-treated tumors with genomics data could further delineate the role of tumor NK cell activation as a potential predictive biomarker." (PMID 34376232, 2021). "A better grasp onto the pathways mediating the action of PD-1 and CTLA-4 blockade on the tumor is important to enhance our ability to monitor for their effects in patients in real time, thereby addressing the uncertainty in treatment outcome following their introduction." (PMID 33602280, 2021). "On the other hand there is inverse association between positive VDR expression in tumor cells and negative and low CTLA4 expression in tumor cells (P= 0.03 and 0.01 respectively)." (PMID 33906311, 2021). "Consequently, ICIs targeting the CTLA-4 pathway aims to counter-act the ability of tumor cells to escape the host immune surveillance by promoting and reactivating tumor-specific T cells." (PMID 33919570, 2021). "Indeed, tumor-intrinsic β-catenin activation prevents T cell priming and infiltration into the tumor microenvironment and results in resistance to anti-PD-L1/anti-CTLA-4 therapy." (PMID 33870463, 2021). "Similar considerations apply to further immunotherapies, that rely on tumor cell lysis mediated by other cytotoxic lymphocytes, especially the inhibition of checkpoints for T cell activation e.g., by anti-CTLA4, anti-PD1 or anti-PDL1 antibodies, as well as therapies with engineered T cells." (PMID 33777033, 2021). "The first one (OP1) finds the less-toxic anti-CTLA4 schedule able to reduce tumor growth." (PMID 35008298, 2021). "In the HCC tumor microenvironment, T-regulators (T-regs) express both CTLA-4 and PD-1." (PMID 34361985, 2021). "Notably, as recently proposed, photodynamic therapy (PDT) combined with CTLA-4 blockade can enhance the cytotoxic CD8+ T-cell response to achieve durable tumor eradication and inducing an immunological memory." (PMID 34571850, 2021). "This may provide a prognostic tool to determine if PD-1 or CTLA-4 therapy promotes T cell activation and infiltration into the tumor." (PMID 33391977, 2021). "Immune checkpoint inhibitors (ICIs) such as anti-programmed death-1 (PD-1) and its ligand PD-L1 and anti-cytotoxic T-lymphocyte antigen 4 (CTLA-4) monoclonal antibodies, are involved in T cell-mediated immune response augmentation and promote anti-tumor immunity." (PMID 33732647, 2021). "CTLA-4 expressed on the surface of tumor cells during the treatment of patients with TNBC may be the target of checkpoint inhibitors and a candidate biomarker for immunotherapy." (PMID 35111680, 2021). "However, response to anti-CTLA4 therapy was significantly impaired in aged animals when tumor growth and survival were compared to young animals." (PMID 34899700, 2021). "Furthermore, CTLA4 tumoral expression (> 1%) was seen in 25 of 52 patients with residual tumor after NAC (48%)." (PMID 33823818, 2021). "However, when combined with anti-PD-L1, anti-CTLA-4 co-treatment generated long-term durable anti-tumor immunity in about 50% of mice." (PMID 34553039, 2021). "A weak tumor-specific T cell response induced by RFA was potentiated by an anti-CTLA-4 blockade." (PMID 34575463, 2021). "Numerous strategies targeting TME have been developed and have achieved considerable treatment efficacy, such as anti-angiogenesis therapy and harnessing effective immune components for elimination of neoplasms, mainly through blockage of immune checkpoints, including PD-1, PD-L1, and CTLA4." (PMID 34831048, 2021).